TGFB1 (transforming growth factor beta 1)
Diseases named in the same sentence as TGFB1 in open-access papers (continued):
Sharing a sentence is not in itself a finding about the gene and the disease.
rectal cancer (17 papers, 2017 to 2025). A primary or metastatic malignant neoplasm that affects the rectum. "Inconsistent with our findings, one clinical study examining an Eastern European cohort of genomically undefined colon and rectal cancers found that increased levels of cytoplasmic TGFβ1 and loss of SMAD4 were associated with reduced tumor-infiltrating macrophages." (PMID 27270652, 2017). "In vitro studies have demonstrated that PUP treatment effectively downregulated immunosuppression in tumor cells, as evidenced by a significant reduction in transforming growth factor beta 1 (TGF-β1) levels in rectal cancer-derived Colon26 cells." (PMID 39885918, 2025). "The underlying correlation between TGFB1 and BMP1 in rectal cancer must be analyzed and identified ulteriorly." (PMID 36267461, 2022). "Previous evidence exhibited that a high expression of TGFB1 may have a worse prognosis by recruiting vasculature, reinforcing invasiveness and metastasis, and highlighting the significance of TGFB1 as a potential immunotherapeutic target of immune checkpoint blockade for rectal cancer." (PMID 36267461, 2022).
abortion (16 papers, 2015 to 2025). the ending of pregnancy by removing a fetus or embryo before it can survive outside the uterus. "To determine whether tregitope treatment restores the Th1/Th2 balance during pregnancy in abortion-prone mice, we examined the levels of IL-2, IL-4, IL-10, IFNγ and TGFβ1 cytokines in blood sera." (PMID 32601347, 2020).
bone metastasis (16 papers, 2006 to 2025). Transfer of a neoplasm from its primary site to bones. "Next, we tested the effect of TGFβ1, an important pro-metastatic factor of the bone metastasis microenvironment, on osteolytic factor secretion." (PMID 20107512, 2010).
Miscarriage (16 papers, 2018 to 2026). A pregnancy that ends at a stage in which the fetus is incapable of surviving on its own, defined as the spontaneous loss of a fetus before the 22th week of pregnancy. "The current research was conducted to investigate the association of VEGFA gene polymorphic variants -2578C>A (rs699947) and -634G>C (rs 2010963) and TGFB1 gene 915G>C (rs1800471) and gene expression level with miscarriage in the first trimester." (PMID 30746337, 2018). "The MDR analysis data have shown the significance for two-locus and three-locus models of the VEGFA and TGFB1 genes with miscarriage." (PMID 30746337, 2018). "The TGFB1 gene mRNA level in decidua and chorion is the same in the condition of miscarriage." (PMID 30746337, 2018). "Literature data on allele frequencies and genotypes investigated VEGFA and TGFB1 SNPs in chorionic tissue in miscarriage in the first trimester are absent." (PMID 30746337, 2018). "The miscarriage risk decreased with simultaneous presence of the VEGFA -634 CG and VEGFA -2578CC genotype (OR 0.38, 95% CI 0.19–0.78, p=0.01) and VEGFA -2578CC, VEGFA -634CG, TGFB1 936CC genotype (OR 0.45, 95% CI 0.21–0.96, p=0.057)." (PMID 30746337, 2018). "Furthermore, the median concentration of TGFβ1 and VEGF was also significantly higher in women whose pregnancies resulted in a live birth (pregnancy success) compared to those who were not pregnant or suffered a miscarriage at both sampling times (Wilcoxon rank-sum test; p < 0.001)." (PMID 40507130, 2025).
pseudoexfoliation glaucoma (16 papers, 2011 to 2026). "Exfoliation glaucoma is associated with high TGFβ1 levels in aqueous humor, indicating a different wound healing process in the filtering bleb compared to POAG." (PMID 39458082, 2024). "Transforming growth factor beta-1 (TGF-β1) has been shown to be increased in exfoliation syndrome (XFS) and XFG eyes and is a key mediator for regulating extracellular matrix homeostasis, reactive oxygen species (ROS) production, and redox balance in the cell milieu." (PMID 36004037, 2022). "In pseudoexfoliation glaucoma (XFG), an aggressive form of secondary open-angle glaucoma, both the latent and active forms of TGFβ1 are increased in the aqueous humour and extracellular matrix (ECM)." (PMID 38920689, 2024).
pulmonary TB (16 papers, 2013 to 2024). "Therefore, the aim of this study was to verify if IFNG, IL12B, TNF, IL17A, IL10, and TGFB1 gene polymorphisms influence the immune response of Brazilian patients with pulmonary tuberculosis (PTB) at different time points of antituberculosis treatment (T1, T2, and T3)." (PMID 23634300, 2013). "Serum levels of TNFa, IL1b, and TGFb1 were found to be related to radiological severity in patients with active pulmonary tuberculosis." (PMID 37834286, 2023).
Salmonella Infections (16 papers, 2012 to 2025). Infections with bacteria of the genus SALMONELLA.
serous ovarian cancer (16 papers, 2014 to 2025). "In serous ovarian cancer, COL6A2 was dysregulated and associated with poor prognosis through the TGFβ1 pathway." (PMID 35036081, 2022). "The upregulation of G6PD, AKR1B1, ITGAV, and TGFβ1 in OVCAR5 CBPR cells was also identified in the tumors of platinum-resistant compared to platinum-sensitive high grade serous ovarian cancer (HGSOC) patients." (PMID 36463238, 2022). "Wnt5A showed a positive correlation with TAZ and TGFβ1 in high- and low-grade serous ovarian cancer specimens compared to borderline serous and normal ovaries." (PMID 35053353, 2022). "We performed the qRT-PCR analysis of TGFβ components (TGFB1, TGFB2, TGFBR1, TGFBR2), Wnt5A/ROR1/ROR2, and Hippo-related genes (YAP1, TAZ, CCN1, and CCN2) in serous ovarian cancer subtypes (LGSOC, HGSOC, BLSOC) compared to the normal ovary." (PMID 35053353, 2022).
chondrosarcoma (15 papers, 2006 to 2026). A malignant cartilaginous matrix-producing mesenchymal neoplasm arising from the bone and soft tissue. "In an immunohistochemical study, a correlation of TGFβ1 and TGFβ2 to the grade of chondrosarcoma has been described." (PMID 23088614, 2012).
cutaneous melanoma (15 papers, 2007 to 2024). A primary melanoma arising from atypical melanocytes in the skin. "Therefore, LTBP4 regulates the progression of skin melanoma via the TGFβ1/Hippo/YAP1 signaling pathway." (PMID 35252214, 2021). "Analysis of transcriptomic data from a skin cutaneous melanoma (SKCM) data set (n = 472), using skin biopsy of healthy women (n = 122) as a reference, showed that upregulation in TGFβ signaling strongly correlated with increased messenger RNA expression levels of TGFB1 and FOXP3." (PMID 29467463, 2018).
Huntington disease (15 papers, 2013 to 2025). Huntington disease (HD) is a rare neurodegenerative disorder of the central nervous system characterized by unwanted choreatic movements, behavioral and psychiatric disturbances and dementia. "We propose several possible scenarios for experimental studies initiated via the extra-cellular ligands TGFB1, FGF2 and TNF aiming at restoring the cellular homeostasis in Huntington's disease." (PMID 27924190, 2016).
intestinal tumor (15 papers, 2007 to 2024). "Recent studies have indicated that chronic inflammation caused either by infection with Helicobacter pylori or Helicobacter hepaticus is a prerequisite for intestinal tumor development in Smad3-/- and Tgfb1-/-; Rag2-/- mice, respectively." (PMID 17615082, 2007).
liver failure (15 papers, 2011 to 2026). A liver disease characterized by the liver losing or has lost all of its function. "Previous studies have shown that TGFβ1 increased in the liver and serum of mice or rats during liver failure." (PMID 33707345, 2021). "Hepatic transforming growth factor beta 1 (TGFβ1) is upregulated due to liver failure in mice and inhibiting circulating TGFβ reduced HE progression." (PMID 30940161, 2019). "In the current study, we observed increased TGFβ1 expression localized primarily to hepatocyte populations due to its co-localization with CK8, supporting findings from our previous work demonstrating TGFβ1 co-localization> with albumin during AOM-induced liver failure." (PMID 30940161, 2019).
mastitis (15 papers, 2015 to 2025). Inflammation of breast tissue during lactation or postpartum due to an obstructed duct or infection. "Because TGFB1 is known for its function in regulating immune responses and involvement in mastitis, it is a striking regulatory candidate." (PMID 32411137, 2020). "Taking this into account, any studies administering TGFβ1 in dairy cows should report prevalence of mastitis in different treatment groups to ensure that TGFβ1 is not predisposing dairy cows to intramammary infections." (PMID 30671288, 2019).
amyloid (14 papers, 2006 to 2025). "Tgfb1 levels were lower in the amyloidosis-induction groups, but not different between the AL cohort and those receiving CR treatment." (PMID 28225824, 2017). "TGF mice overexpress a constitutively active form of TGFβ1 in brain astrocytes and recapitulate aspects of the cerebrovascular pathology seen in VCID and AD (but not the amyloid pathology)." (PMID 38132326, 2023).
cutaneous leishmaniasis (14 papers, 2012 to 2025). Leishmaniasis affecting the skin. "In the healing process of cutaneous leishmaniasis caused by L. braziliensis, a higher expression of TGFβ1 was more associated with acute infection and failure or relapses after treatment, and the higher levels of EGF were associated with adequate wound healing." (PMID 39808642, 2025).
prostate adenocarcinoma (14 papers, 2011 to 2025). "A PanCancer Atlas cohort of 494 prostate adenocarcinoma patients revealed a positive correlation between MIR100HG and TGFB1 expression, and even stronger correlation between MIR100HG and TGFBI expression." (PMID 33941855, 2021).
vitiligo (14 papers, 2015 to 2024). Generalized well circumscribed patches of leukoderma that are generally distributed over symmetric body locations and is due to autoimmune destruction of melanocytes. "Highly significant changes in the expression of T cell activation-related genes IFNG, FASLG, GZMA and IL21 and anti-inflammatory genes IL10 and TGFB1 were found in growing feathers of vitiligo-expressing Smyth chickens (P < 0.0001)." (PMID 38720888, 2024).
hypothyroidism (13 papers, 2010 to 2026). Abnormally low levels of thyroid hormone. "In particular, the pro-fibrotic TGFβ1 isoform may contribute to the progression of HT and development of hypothyroidism." (PMID 39023839, 2024). "Additionally, transforming growth factor beta-1, which stimulates vascular smooth muscle cells to secrete cystatin C, is significantly reduced in hypothyroidism." (PMID 38416371, 2024).
intrahepatic cholangiocarcinoma (13 papers, 2015 to 2025). A carcinoma that arises from the intrahepatic bile duct epithelium in any site of the intrahepatic biliary tree. "This study developed a Trojan horse nanotherapy strategy targeting the cPKM‐STMN1/TGFB1 axis for intrahepatic cholangiocarcinoma (ICC)." (PMID 37789644, 2023).
metastatic melanoma (13 papers, 2012 to 2024). A melanoma that has spread from its primary site to another anatomic site. "A recent study reported that chemotherapy-responsive metastatic melanoma patients had higher serum TGFβ1 levels compared with chemotherapy-unresponsive patients (p = 0.05)." (PMID 26380086, 2015). "We first confirmed that primary and metastatic melanoma specimens express similar TGFB1 transcript levels, and found a direct correlation with the expression of SERPINE1 (PAI-1), a downstream target of TGF-β signaling (which we initially used as the reporter gene in our TGF-β assay in vitro)." (PMID 28448494, 2017).
thyroid tumor (13 papers, 2013 to 2024). A benign or malignant neoplasm affecting the thyroid gland. "Moreover, it has been discovered that BRAFV600E increases exclusively TGFβ1 secretion through the MEK/ERK pathway in thyroid tumour cells." (PMID 32825554, 2020).
viral hepatitis (13 papers, 2005 to 2025). An acute or chronic inflammation of the liver parenchyma caused by viruses. "In the context of chronic viral hepatitis, systemic inflammation may moderate TGFβ1‐related neuroinflammatory responses and the resultant cognitive functions, providing a mechanistic link between TGFβ1 polymorphisms, viral hepatitis, and altered cognitive functions." (PMID 38970443, 2024). "This study investigated the influence of TGFB1 genetic polymorphisms on cognitive function in individuals with and without hepatitis infections, hypothesizing that these polymorphisms and the viral hepatitis‐induced inflammatory environment interact to affect cognitive abilities." (PMID 38970443, 2024). "Our findings underscore the significant role of TGFβ1 in cognitive function and the moderating impact of viral hepatitis on TGFB1 SNP effects." (PMID 38970443, 2024).
autoimmune thyroid disease (12 papers, 2020 to 2025). Inflammatory disease of the thyroid gland due to autoimmune responses leading to lymphocytic infiltration of the gland. "The study concluded that cortisol, in addition to estrogen and transforming growth factor-beta 1 (TGF-β1), was associated with suppression of thyroid autoimmunity in the pregnancy and postpartum period." (PMID 37868409, 2023).
CARASIL (12 papers, 2010 to 2022). CARASIL is a hereditary cerebral small vessel disease characterized by early-onset gait disturbances, premature scalp alopecia, ischemic stroke, acute mid to lower back pain and progressive cognitive disturbances leading to severe dementia. "Transforming growth factor beta 1 (TGFB1) is dysregulated in the hereditary SVD, CARASIL (cerebral autosomal recessive arteriopathy with subcortical infarcts and leukoencephalopathy)." (PMID 28470822, 2018).
dry eye (12 papers, 2011 to 2025). "The dry eye syndrome secondary to the direct effects on the lacrimal acinar cells of prolactin, transforming growth factor beta 1 (TGF-β1), and epidermal growth factor is found at the level of the lacrimal apparatus." (PMID 34441264, 2021).
kidney cancer (12 papers, 2014 to 2025). Primary or metastatic malignant neoplasm involving the kidney. "Infiltrating CD4+ T cells fascinate TGFβ1 expression and regulated kidney cancer cell proliferation by activating TGFβ1/YBX1/HIF2α signals." (PMID 35096961, 2021). "For example, it collaborates with the TGF-β1 (TGFB1 pathway to promote epithelial-to-mesenchymal transition (EMT), as well as for profibrotic and invasion responses in breast, lung, and kidney cancer cell lines." (PMID 36494864, 2022).
nematode infection (12 papers, 2014 to 2024). "Our results confirm that EL4 cells produce TGFβ-1 in vitro, that nematode infection enhanced the concentration of TGF-β in mouse serum in vivo, and that this elevation was associated with different forms of metastatic foci in the lungs." (PMID 32960348, 2020).
renal dysfunction (12 papers, 2012 to 2025). "We found variant A allele carriers of rs4803455 C > A, located in intron 2 of TGFB1, had lower odds of renal dysfunction compared to C/C homozygotes." (PMID 33868389, 2021). "Specifically, TGFB1 rs4803455 variant A carriers had lower odds of renal dysfunction when compared to participants with the C/C genotype [odds ratio (OR) 0.28; 95% CI 0.12–0.62; p = 0.002]." (PMID 33868389, 2021). "Renal dysfunction was present in 43% of participants with the TGFB1 rs4803455 C/C genotype vs. 22% of variant A carriers, and 20% of participants with the PLCB1 rs170549 G/G genotype vs. 39% of variant A carriers." (PMID 33868389, 2021). "Two SNVs, TGFB1 rs4803455 and PLCB1 rs170549, were associated with renal dysfunction 1-year post-transplant after accounting for an FDR of 20%." (PMID 33868389, 2021). "Nonetheless, our results, in combination with previous findings, suggest that SNVs in TGFB1 may play a role in the development of renal dysfunction following heart transplantation." (PMID 33868389, 2021). "Two SNVs [transforming growth factor beta 1 (TGFB1) rs4803455 C > A and phospholipase C beta 1 (PLCB1) rs170549 G > A] were significantly associated with renal dysfunction 1-year post-transplant in the univariate analyses after adjusting for an FDR of 20% (unadjusted p = 0.004 for both SNVs)." (PMID 33868389, 2021). "Novel genetic markers, such as TGFB1 rs4803455 and PLCB1 rs170549, may serve as tools that clinicians can utilize to assess a patient’s risk of CNI-associated renal dysfunction following heart transplantation, thereby improving clinical care and advancing precision medicine in this population." (PMID 33868389, 2021). "Pharmacogenetic markers, such as TGFB1 rs4803455 and PLCB1 rs170549, could help identify patients at increased risk of CNI-associated renal dysfunction following HTx, potentially allowing clinicians to provide more precise and personalized care to this population." (PMID 33868389, 2021). "In conclusion, we provide additional evidence that SNVs in the pro-fibrotic TGFB1 and cell signaling PLCB1 genes may play a role in the development of renal dysfunction in adult heart transplant recipients taking CNIs." (PMID 33868389, 2021).
skin aging (12 papers, 2020 to 2026). The gradual irreversible changes in structure of skin that occur as a result of the passage of time.. "Although our transgenic animals are not a skin aging model, it has been shown that platelet‐derived mediators such as TGFβ1 are lower in older individuals, suggesting that a loss in platelet‐derived TGFβ1 with age may contribute to the histological changes of skin aging." (PMID 32068954, 2020).
thrombosis (12 papers, 2016 to 2025). "Moreover, TGFB1 has been linked to accelerated thrombus formation by inducing platelet aggregation and the expression is increased in rats with traumatic deep vein thrombosis versus control rats." (PMID 28829817, 2017). "After filtering the plasma proteomic data from UK Biobank (UKB) participants diagnosed with I63.0 (cerebral infarction due to thrombosis) or I63.4 (cerebral infarction due to embolism), we assessed the correlation between plasma CD163 and TGFB1 levels." (PMID 41329022, 2025).
thyroid (12 papers, 2013 to 2025). "Kristensen’s study showed greater expression of TGFβ1 messenger in thyroiditis as compared to controls." (PMID 36578493, 2022). "Furthermore, we analyzed the mRNA expression pattern of TGFB1, TGFBR1, and TGFBR2 in malignant and benign thyroid tissues." (PMID 33905626, 2021).
autoimmune hepatitis (11 papers, 2017 to 2025). Hepatitis caused by autoantibodies. "In the autoimmune hepatitis (AIH) mouse model, the accumulation of CD11b+Gr-1+ myeloid cells was observed in the BALB/c Tgfb1−/−liver." (PMID 30670926, 2018).
bladder tumors (11 papers, 2009 to 2023). "In the animal experiment, MSCs could favor VX2 bladder tumor growth and up-regulate the expression of TGFβ1, EGF, FAPa, MMP9 in VX2 tumor tissue." (PMID 31528217, 2019). "However, neither TGFB1 +869T>C nor +915G>C polymorphisms showed any association with tumor relapse and progression in bladder tumors without muscular invasive in a Spanish population." (PMID 19566948, 2009). "Findings from our study provide compelling evidence for co-expression of multiple immune checkpoint genes including, PD-1, PD-L1, IDO1, TIGIT, TIM-3, TGFB1, LAG3, and others, that potentially contribute to compensatory immune evasion in bladder tumors." (PMID 31174611, 2019).
eczema (11 papers, 2011 to 2025). "Some studies support this observation, having found increased TGFβ1 and TGFβ2 in colostrum associated with the eczema onset in infants." (PMID 28538696, 2017).
endotoxemia (11 papers, 2009 to 2026). "Monocytes/macrophages are known to express uPAR, and levels of expression are reported to be elevated during endotoxemia and by various cytokines including IL-1β, TNF-α, and TGFβ1." (PMID 19459212, 2009).